RN7SL544P (RNA, 7SL, cytoplasmic 544, pseudogene)
Gene: Miscellaneous RNA gene on chromosome 9 (62,363,581 to 62,363,864, forward strand). Ensembl gene ENSG00000275230.
Homologues: Orthologues: chimpanzee Metazoa_SRP (99% identical), macaque Metazoa_SRP (94% identical). Paralogues in human: RN7SL763P (100% identical), RN7SL787P (99% identical), RN7SL565P (99% identical), RN7SL722P (99% identical), RN7SL52P (99% identical), RN7SL205P (97% identical), RN7SL1 (81% identical), RN7SL2 (81% identical), RN7SL3 (81% identical), RN7SL322P (80% identical), RN7SL230P (80% identical), RN7SL709P (80% identical), and 706 more.